IL1B (interleukin 1 beta)
Diseases named in the same sentence as IL1B in open-access papers (continued):
Sharing a sentence is not in itself a finding about the gene and the disease.
type 1 diabetes (continued). "During the initial stage of type 1 diabetes, prolonged exposure of pancreatic β-cell to proinflammatory cytokines such as IL-1β, TNF-α, and IFN-γ results in a decreased capacity to produce and release insulin, as well as cell loss by apoptosis." (PMID 34054343, 2021). "During the initial stage of type 1 diabetes, β-cells are exposed to the proinflammatory cytokines, such as IL-1β, IFN-γ, and TNF-α, released by the infiltrated immune cells." (PMID 34054343, 2021). "Inhibition of caspase-1 or deletion of IL-1 receptor prevented IL-1β-dependent formation of acellular capillaries in retinas of type 1 diabetic mouse models." (PMID 32492941, 2020). "One of the important mechanisms of beta cell damage during type 1 diabetes is increased expression of proinflammatory cytokines such as IL-1β, IFN-γ and TNF-α and cytokine induced beta cells were commonly used as in vitro model of type 1 diabetes." (PMID 30974824, 2019). "The blockage of TNF-α, eternacept, IL-1β, and anakinra was administered in three patients with type 1 diabetes before and during islet transplantation and all patients achieved insulin independence with normal HbA1c levels by a single infusion from one donor." (PMID 31652814, 2019). "Patients with type 1 diabetes exhibited increased circulating mDNA as well as caspase-1 and IL-1β activation." (PMID 32009974, 2019). "In the onset of type 1 diabetes as well as in islet transplantation, IL-1β is one of the cytokines involved in the recruitment of immune cells in islets and eventually in islet destruction." (PMID 29941940, 2018). "Previous studies report that microvascular blood flow preceding pancreatitis is increased in type 1 diabetes, and the level of Il-1β in the pancreas is locally elevated." (PMID 30439990, 2018). "The cytokine interleukin-1β (IL-1β) is known to stimulate proinflammatory immune responses and impair β-cell function and viability, all critical events in the pathogenesis of type 1 diabetes (T1D)." (PMID 26953152, 2016). "IL-1β is expressed and secreted by adipose tissue and is a proinflammatory cytokine that plays an important role in pancreatic β-cell destruction in type 1 diabetes." (PMID 25918733, 2015). "A central aspect of the pathogenesis of diabetes is mediated via interleukin-1β (IL-1β), which is released by infiltrating inflammatory cells in the pancreas in type I diabetes." (PMID 26180580, 2015). "IL-1β is a proinflammatory cytokine which has been proposed to play a role in inflammatory pancreatic β-cell destruction leading to type 1diabetes." (PMID 25887648, 2015). "Endogenous synthesis of IL-1β is diminished in nerve tissue in type 1 diabetes and we propose this defect triggers reduced STAT3 signaling and mitochondrial function leading to sup-optimal axonal regeneration and plasticity." (PMID 24152426, 2013). "Inflammatory mediators released from macrophages, such as IL-1β and TNFα, play a key role in early stages of type 1 diabetes." (PMID 24191154, 2013). "In the course of Type 1 diabetes pro-inflammatory cytokines (e.g., IL-1β, IFN-γ and TNF-α) produced by islet-infiltrating immune cells modify expression of key gene networks in β-cells, leading to local inflammation and β-cell apoptosis." (PMID 22347430, 2012). "Proinflammatory cytokines, including IL-1β (interleukin 1β), TNFα (tumor necrosis factor α), and IFNγ (interferon γ), released from immune cells infiltrating the pancreas in Type 1 diabetes, target the β-cells via their respective receptors." (PMID 20182529, 2010). "It is evident from studies in patients with diabetes and in animal models of Type 1 diabetes, that IL-1β is the key proinflammatory cytokine which significantly contributes to β-cell dysfunction and apoptosis in the pathogenesis of Type 1 diabetes." (PMID 20182529, 2010). "IL-1β blockade has been shown to reduce cardiac fibrosis, intestinal cell death in a model of small intestine enteropathy, and beta islet cell death in a rat model of type I diabetes." (PMID 39763850, 2024).
type 1 diabetes (continued). "Interleukin 1β (IL1β) is a pro-inflammatory cytokine that may play a crucial role in enteric neuroinflammation in type 1 diabetes." (PMID 36982878, 2023). "Furthermore, we detected higher IL-1β production upon lipopolysaccharide stimulation in the PBMCs from type 1 diabetes patients, which was attenuated by OI treatment." (PMID 36918798, 2023). "Furthermore, high maternal levels of circulating inflammatory cytokines (IFN-γ, IL-1β, CCL2, and CCL4) during pregnancy have been associated with increased risk of type 1 diabetes in the offspring." (PMID 35693790, 2022). "Moreover, the study revealed a hyperglycemic environment promotes the activation of NF-κB signaling pathway, upregulates the expression of TNF-α, MCP-1, and IL-1β, thereby contributing to the renal damage in type 1 diabetic mice." (PMID 34253875, 2022). "We presently used a 7-stage protocol to generate beta cells from human iPSC and evaluated whether these cells are responsive to the pro-inflammatory cytokines (IFNγ, IL-1β, or IFNα) that play a role in type 1 diabetes." (PMID 31900242, 2020). "Organelles such as the ER, mitochondria, and nucleus are also affected by cytokine like IL-1β which may lead to β-cell death in type 1 diabetes (T1D) and type 2 diabetes (T2D)." (PMID 33354575, 2020). "Proinflammatory cytokines (such as IFN-γ, TNF-α, and interleukin 1β (IL-1β)) promote beta-cell destruction and exacerbate autoimmunity, which may ultimately lead to type 1 diabetes (T1D)." (PMID 31443415, 2019). "The modified cells were then exposed to proinflammatory cytokines mimicking the pathogenic inflammatory beta cell microenvironment of pancreatic islet in type 1 diabetes, i.e. IFNγ/IL1β or IFNγ/IL1β/TNFα and analysed for endogenous XBP1 splicing by qPCR or light emission in cell lysates." (PMID 30532033, 2018). "IL-1β and other cytokines induce upregulation of the inducible form of nitric oxide synthase (iNOS), leading to the production of nitric oxide and downstream β-cell damage and death in the pancreatic islets and thus type I diabetes." (PMID 26180580, 2015). "Similarly, with chronic exposure to IL-1β, BK-induced Ca2+ mobilization was accentuated in cells from type 1 diabetics compared to the controls." (PMID 24466329, 2014). "There was only one study in type 1 diabetes Caucasian population for the SNP IL1B in the IL-1 gene." (PMID 25280384, 2014). "As Il-1β, IFNγ and TNFα are important cytokine effectors of β-cell death in type 1 diabetes, we next sought to determine whether Myt3 is reduced by immune-cell attack in non-obese diabetic (NOD) mice." (PMID 23236509, 2012). "During the course of type 1 diabetes, autoreactive immune cells secrete copious amount of inflammatory cytokines such as IL-1β, TNF-α, and IFN-γ into the islet milieu, which stimulate excessive production of NO in β cells and mediate β-cell destruction by inducing ER stress." (PMID 22454627, 2012). "In the early stage of type 1 diabetes, the autoreactive immune cells such as macrophages and T lymphocytes infiltrate into the pancreatic islets along with the secretion of inflammatory cytokines such as IL-1β, IFN-γ, and TNF-α, which then induce ER stress to mediate β-cell destruction." (PMID 22454627, 2012). "One of the main reasons for the development of type I diabetes is that cytokines such as IFN-γ, TNF-α, and IL-1β produced by immune cells break down the islet beta cells." (PMID 36386181, 2022). "IFN-γ, IL-1β, and TNF-α production by autoreactive Th1 cells is involved in the destruction of insulin-secreting β-cells in type 1 diabetes." (PMID 35652039, 2022). "Macrophages not only induce β cell damage or death by releasing TNF-α, IL-1β, and ROS but also promote efficient differentiation of diabetogenic CD8+CTLs leading to type 1 diabetes onset." (PMID 33690220, 2021). "One of the KEGG pathways that showed enrichment was “Type I diabetes mellitus” and the analyzed module contains two genes from this pathway—FAS and IL1B." (PMID 27257970, 2016).
type 1 diabetes (continued). "Both IL-1β and TNF-α contribute to pancreatic β-cell death in type 1 diabetes probably via activation of transcription factor nuclear factor-kappa-B (NF-kappaB)." (PMID 19243577, 2009). "Using high-throughput RNA sequencing data from human islets and EndoC-βH1 cells exposed to IFNα or IFNγ/IL1β, we evaluated the role of ADAR1 in human pancreatic β cells and determined the impact of the type 1 diabetes pathophysiological environment on ADAR1-dependent RNA editing." (PMID 36518246, 2022). "In addition, the topical application of propolis on diabetic wounds has reduced/declined IL-1β, IL-6, TNF-α, and MMP9 levels in STZ-induced type I diabetic mice." (PMID 35047540, 2021). "The results showed that diacerein, via modulation of proinflammatory cytokines (IL-1β and TNF-α), interferes with the onset of type 1 diabetes and may alter the incidence of autoimmune diabetes in treated animals." (PMID 29805981, 2018). "Moreover, monocytes isolated from patients with type 1 diabetes also present a proinflammatory phenotype and secrete higher levels of inflammatory cytokines, such as IL-6 and IL-1β, compared with nondiabetic individuals." (PMID 29850615, 2018). "As TYK2 inhibition has raised as a potential therapeutic target for the prevention or treatment of type 1 diabetes, we investigated whether the selective TYK2 inhibitor deucravacitinib could protect β-cells from the effects of IFNα and other proinflammatory cytokines (i.e., IFNγ and IL-1β)." (PMID 37854597, 2023).
Crohn disease (101 papers, 2006 to 2025). A gastrointestinal disorder characterized by chronic inflammation involving all layers of the intestinal wall, noncaseating granulomas affecting the intestinal wall and regional lymph nodes, and transmural fibrosis. "In the case of IL1B (rs1143634), the Qatari population had the GG genotype frequency of 40.5%, which was associated with lower response to Infliximab in Crohn’s disease patients." (PMID 41346622, 2025). "Current clinical studies have revealed that there are high-profile inflammatory markers in subjects with Crohn’s disease, specifically activated monocyte/macrophage-associated markers such as IL-1β and chemokine CXCL16." (PMID 40806424, 2025). "Studies in context with other inflammatory conditions such as on adult-onset Still’s disease (AOSD) or Crohn’s disease similarly suggest an association of IL-1β and LRG1 expression." (PMID 35699824, 2022). "This discovery suggests the need for further studies to determine the frequency of excess IL-1β secretion in Crohn's disease patient populations due to CARD8 mutations or other abnormalities of the NLRP3 inflammasome." (PMID 30455704, 2018). "Of particular importance is the discovery that increased NLRP3 inflammasome activity occurring because of loss of CARD8 inhibition of the inflammasome can be a cause of Crohn's disease which responds only to treatment involving IL-1β inhibition." (PMID 30455704, 2018). "Another instance in which increased IL-1β secretion has been linked to IBD was reported in Crohn's disease patients bearing a Crohn's disease risk polymorphism in the TPL2 gene that is associated with increased TPL2 expression." (PMID 30455704, 2018). "Patients with CARD8 mutations and excessive IL-1β production leading to Crohn's disease are in principle similar to patients with IL-10 abnormalities since in both cases increased NLRP3 inflammasome hyperactivity is due to lack of an inflammasome inhibitor." (PMID 30455704, 2018). "IL-1β is one of the cytokines increased in patients with Crohn’s disease and associated with inflammation in this disorder." (PMID 24352087, 2013). "Furthermore, mutations in the downstream regulatory region of NLRP3 have also been shown to be associated with decreased IL-1β expression and increased susceptibility to Crohn’s disease (CD) in humans." (PMID 40227443, 2025). "Notably, the ATG16L1 T300A Crohn’s disease variant associated with dysfunctional autophagy flux is known to impact Th1 responses as well as IL-1β-secretion." (PMID 38548722, 2024). "ATG16L1 polymorphisms together with the excessive production of IL-1β and IL-6 in human peripheral mononuclear cells may account for the chronic inflammatory process in Crohn’s disease." (PMID 33020418, 2020). "Furthermore, polymorphisms of the NLRP3 gene lead to hypo-production of IL-1β that is associated with increased risk of developing Crohn’s disease." (PMID 28824627, 2017). "Defective autophagy has been shown to promote IL-1β release in several inflammatory conditions, including Mycobacterium tuberculosis infection and Crohn ́s disease." (PMID 40276384, 2025). "Despite these limitations, the results of first study were clear in showing that circulating cells from patients with Crohn’s disease exhibited significantly higher mean NLRC4-induced IL-1β and IL-18 responses than cells from control individuals." (PMID 41246319, 2025). "Specifically, the activated monocyte/macrophage-associated markers IL-1β and CXCL16 were declined post-treatment, highlighting the potential of Stem Cell Educator therapy for the clinical management of patients with Crohn’s disease." (PMID 40806424, 2025). "Notably, researchers have found that IL-1α/IL-1β and IL-10 are critical regulators of monocyte IL-23 production, distinguishing homeostatic IL-23 production from inflammation-associated IL-23 production in patients with severe ulcerative active Crohn’s disease." (PMID 40564117, 2025).
Crohn disease (continued). "Mucosal IL-1β mRNA levels were elevated in human patients affected with eosinophilic colitis and Crohn’s disease, and elevated IL-1β mRNA levels indicated patients with early clinical relapse of Crohn’s disease." (PMID 36670767, 2023). "Our findings were consistent with a previous report, which showed that CD14+ macrophages in Crohn’s disease consisted of IL-1β producing CD163−/dim cells." (PMID 37344477, 2023). "Th17 cells were differentiated from CD4 cells obtained from the peripheral blood of healthy controls and Crohn’s disease patients, upon in vitro exposure to IL-6, IL-1β, and TGF-β5,18,22." (PMID 36131123, 2022). "Like in current study, pro-inflammatory cytokines (IL-1β and IL-6) and chemokine (IL-8) were downregulated, and this was demonstrated ex vivo with heparinized blood of exposed Colitis Ulcerosa, Crohn’s Disease and normal patients." (PMID 34886904, 2021). "TLR-4 and IL-1β are overexpressed in the intestinal epithelium of patients with Crohn's disease (diarrhoea)." (PMID 32733972, 2020). "Our data are in agreement with previous reports showing that oral supplementation of Ab improved Crohn's disease through the reduction of systemic pro-inflammatory cytokines such as IL-1β, IL-6 and G-CSF." (PMID 32714320, 2020). "Anti-TNFα therapy up-regulated IL6 and IL23p19, in patients with Crohn’s disease; IL-1B and IL17A remained up-regulated in patients refractory to anti-TNF α." (PMID 33193322, 2020). "During Crohn's disease, IL-1β is significantly raised and there is a positive correlation between the severity of mucosal inflammation and the levels of IL-1β." (PMID 31191826, 2019). "Increased production of IL-1β and TNFα in inflamed Crohn's disease mucosa induces the synthesis of IL-8, which is an effective neutrophil chemoattractant." (PMID 31191826, 2019). "IL-1β and TNFα expression in patients with Crohn’s disease has been shown to lead to increased intestinal permeability." (PMID 30755679, 2019). "The high concentrations of IL-1β in the intestine of patients with Crohn's disease are mainly attributed to local mononuclear cell infiltration, which were also observed in this model." (PMID 31191826, 2019). "Expression of pro-inflammatory cytokines: IL-1α, IL-1β, TNFα, and IL-15 were increased in IL-1rn-/- mice, and these results are in agreement with those obtained from patients with Crohn's disease." (PMID 31191826, 2019). "Particularly in Crohn disease, recent evidence suggests involvement of abnormal macrophage function with increased IL-1β secretion and impaired bacterial killing." (PMID 24312491, 2013). "Similar to the intestinal DCs in patients with Crohn's disease, murine IL-10-/- DCs produced more IL-1β than their wild-type counterparts and promoted Th17 cell development in an IL-1-dependent manner." (PMID 22176654, 2011). "The ability of NRLs to regulate, for example, nuclear factor-kappa B (NF-κB) signalling and interleukin-1-beta (IL-1β) production, indicates that they are important for the pathogenesis of inflammatory human diseases, such as Crohn’s disease." (PMID 22254115, 2011). "Here it should be mentioned first that whereas IL-1β levels are increased in Crohn’s disease and, as such, are part of the potent pro-inflammatory cytokine package driving this inflammation, it has not been established that this cytokine plays an indispensable pro-inflammatory role in most patients." (PMID 41246319, 2025). "-Higher IL-1β levels, and supports Crohn’s disease pathogenesis." (PMID 38920661, 2024). "Earlier studies also indicated that human beta-defensins (hBDs), which are chemotactic to T cells and induce the mRNA expression of IL-1β, IL-6, and IL-22, may have copy number variations in Crohn’s disease." (PMID 38246944, 2024). "Indeed, the increase of CEMIP expression is observed after stimulation with TNF-α in OA chondrocytes, IL-6 in Crohn’s disease fibroblasts and IL-1β in pancreatic ductal adenocarcinoma cell line." (PMID 35474501, 2022).